XKR9 (XK related 9)
Description:
[XK-related protein 9, processed form]: Phospholipid scramblase that promotes phosphatidylserine exposure on apoptotic cell surface. Phosphatidylserine is a specific marker only present at the surface of apoptotic cells and acts as a specific signal for engulfment.
Synonyms: hXKR9; XRG9
Tractability: Antibody: UniProt places it where antibodies can reach, with medium confidence; UniProt predicts a signal peptide or a membrane-spanning region; its Gene Ontology location is reachable by antibodies, with medium confidence.
Gene: Protein-coding gene on chromosome 8 (70,669,332 to 70,790,371, forward strand). Ensembl gene ENSG00000221947.
Subcellular location: Cell membrane
Subcellular location (Human Protein Atlas): Mitochondria
Gene Ontology:
Cellular component: membrane; plasma membrane
Genetic constraint (gnomAD): Loss-of-function variants: 32 observed, 32.77 expected, observed/expected ratio (o/e) 0.98, 90% interval 0.74 to 1.31. The upper end of that interval is the gene's LOEUF score, 1.31, which puts it in group 5 of 6, group 1 being the genes least tolerant of losing a copy. Missense variants: 546 observed, 449.86 expected, observed/expected ratio (o/e) 1.21, 90% interval 1.13 to 1.3. Synonymous variants: 168 observed, 150.86 expected, observed/expected ratio (o/e) 1.11, 90% interval 0.98 to 1.27.
Homologues: Orthologues: chimpanzee XKR9 (99% identical), macaque XKR9 (95% identical), rabbit XKR9 (83% identical), dog XKR9 (83% identical), pig XKR9 (82% identical), mouse Xkr9 (77% identical), rat Xkr9 (76% identical), tropical clawed frog xkr9 (45% identical), zebrafish xkr9 (38% identical), Drosophila melanogaster CG18635 (16% identical). Paralogues in human: XKR8 (29% identical), XKR4 (27% identical), XKR6 (26% identical), XKR7 (25% identical), XKR5 (19% identical).
Diseases named in the same sentence as XKR9 in open-access papers:
XKR9 is named in the same sentence as 5 diseases in open-access papers, as found by Europe PMC text mining. Sharing a sentence is not in itself a finding about the gene and the disease. The quoted sentences say what the papers report.
holoprosencephaly (1 paper, 2022). Holoprosencephaly (HPE) is a complex brain malformation resulting from incomplete cleavage of the prosencephalon, occurring between the 18th and 28th day of gestation, and affecting both the forebrain and face, which results in neurological manifestations and facial anomalies of variable severity. "AD, PD, and MG all had SNPs in PTCH1 (associated with holoprosencephaly) and XKR9 (associated with otofaciocervical syndrome)." (PMID 35711735, 2022).
cancer (2 papers, 2020 to 2026). A tumor composed of atypical neoplastic, often pleomorphic cells that invade other tissues. "Bayesian network modeling showed that XKR9 is linked to important cancer‐related genes, including FOXM1, cyclin B1, and RB1CC1 (RB1 regulator)." (PMID 32920960, 2020). "One of the DEGs, XKR9, was found to be associated with overall survival for all of the cancers combined as well as for three individual cancer types." (PMID 32920960, 2020). "Among them, XKR9 gene expression was found to be significantly associated with overall survival for all cancers combined as well as for several individual cancers." (PMID 32920960, 2020). "We used UCSC genome browser to find the location of the SNP, rs17689585, which was found to be associated with XKR9 gene expression and may be a potential driver SNP for cancer racial disparity." (PMID 32920960, 2020). "The observation that higher expression of XKR9 is associated with lower survival probability also suggests that targeting on XKR9 may be worth exploring as a potentially new therapeutic direction in cancer immunotherapy." (PMID 32920960, 2020). "XK Related 9 (XKR9), associated with cancer survival outcomes, represents a potential target for cancer immunotherapy." (PMID 41123022, 2026). "XKR9 was found to be down‐regulated in AS cancer patients in both the AS vs. CA comparison (log2 fold change = −1.58; adjusted p‐value = 1.50e‐39) and the AS vs. AA comparison (log2 fold change = −1.08; adjusted p‐value = 6.01e‐08)." (PMID 32920960, 2020). "A literature search for XKR9 returned little information on its function and its relationship with cancer." (PMID 32920960, 2020). "From both upstream and downstream proteins/genes identified by the BN, XKR9 likely plays some intriguing functions in cancer." (PMID 32920960, 2020). "XKR9 was found to be differentially expressed in all three pairwise comparisons of combined data for all cancers." (PMID 32920960, 2020). "The BN model links XKR9 expression with tumor growth and apoptosis, which may explain its effect on overall survival of cancer patients." (PMID 32920960, 2020). "Our results point to the interesting hypothesis that XKR9 could be a novel drug target for cancer immunotherapy." (PMID 32920960, 2020). "Since some of the DE genes may be associated with race only, but not cancer, survival analysis using the DE genes was conducted to find DE genes that are significantly associated with overall survival of the cancer patients (XKR9 and CST1 were found in this study)." (PMID 32920960, 2020).
XKR9 also shares sentences with these, for which no sentence is quoted: kidney chromophobe (1 paper); otofaciocervical syndrome (1); tumor (1).